ZDHHC9 (zDHHC palmitoyltransferase 9)
Diseases named in the same sentence as ZDHHC9 in open-access papers (continued):
Sharing a sentence is not in itself a finding about the gene and the disease.
tumor (continued). "In addition, the glucose transporter GLUT1 is palmitoylated by ZDHHC9 to enhance glycolysis, providing energy for tumor progression." (PMID 36577755, 2022). "Moreover, ZDHHC9 overexpression promotes an immunosuppressive ‘cold tumor’ microenvironment." (PMID 40977744, 2025). "This comprehensive understanding significantly strengthens the rationale for ZDHHC9 as a novel target for BC treatment and supports its prognostic value in identifying patients who might benefit from therapies counteracting tumor palmitoylation-dependent pathways." (PMID 40740766, 2025). "Functionally, PA accelerates xenograft growth, whereas targeting ZDHHC9 and FATP2 inhibits c-Myc function to suppress tumor burden." (PMID 41698889, 2026). "Recent studies have demonstrated that ZDHHC9 mediates the S‐palmitoylation of GLUT1 and CD38, thereby stabilizing their membrane clustering with implications for tumor progression." (PMID 40828036, 2025). "The tumor microenvironment (TME) and single-cell data were further evaluated to understand the link between ZDHHC9 expression and immune cell infiltration." (PMID 40740766, 2025). "Ligand–receptor interaction mapping revealed that tumor-derived MIF and macrophage-expressed CD74 (with co-receptor CD44) form a signaling axis in ZDHHC9-high tumors." (PMID 40740766, 2025). "Both ZDHHC9 and ZDHHC20 exhibit characteristics of potential tumor biomarkers, supported by multiple datasets and clinical correlations." (PMID 40335986, 2025). "Altogether, these results suggest that ZDHHC9 plays a negative regulatory role in the infiltration of CD8 + T cells and NK cells within tumor tissues." (PMID 37875591, 2023). "Furthermore, blocking GLUT1 palmitoylation mediated by knockout of ZDHHC9, the enzyme that palmitoylates GLUT1, impaired glycolysis and reduced GBM tumor growth." (PMID 37759431, 2023).
neurodevelopmental disorder (3 papers, 2020 to 2025). A behavioral and cognitive disorder with onset during the developmental period that involves impaired or aberrant development of intellectual, motor, or social functions. "This study tested the hypothesis that empirical neurophysiological differences between a monogenic neurodevelopmental disorder group (ZDHHC9‐associated ID) and control group are compatible with reduced inhibition in a network model of auditory processing." (PMID 40308169, 2025).
neurodegenerative disease (2 papers, 2021 to 2022). A disorder of the central nervous system characterized by gradual and progressive loss of neural tissue and neurologic function. "We found that PIKfyve is acylated by the two acyltransferases, zDHHC9/21, which are highly expressed in the brain and are associated with neurodegenerative diseases." (PMID 34291577, 2021).
genetic disorders (1 paper, 2016). "This is true for groups with genetic disorders like children with mutations in FOXP2 and ZDHHC9; whilst there is a single causal gene, the cognitive and behavioural impairments associated with this mutation will impact upon cognitive development more broadly." (PMID 27747153, 2016).
immune diseases (1 paper, 2025). "Conversely, the low ZDHHC9 expression cohort was enriched in pathways linked to the immune system, immune diseases, and environmental information processing." (PMID 40740766, 2025).
ZDHHC9 also shares sentences with these, for which no sentence is quoted: infection (3 papers); adenocarcinoma (2); brain tumor (2); gastric cancer (2); lung carcinoma (2); speech disorder (2); type 1 diabetes (2); adenoma (1); chronic kidney disease (1); cognitive disorder (1); diabetes mellitus (1); diabetic nephropathy (1); dilated cardiomyopathy (1); fibrosis (1); Huntington disease (1); IgA nephropathy (1); lymph node metastases (1); lymphoma (1); membranous nephropathy (1); metastatic cancer (1); multiple myeloma (1); myeloma (1); Obesity (1); oropharyngeal squamous cell carcinoma (1); pancreatic adenocarcinoma (1); primary pulmonary hypertension (1); rectal adenocarcinoma (1); renal cell carcinoma (1); Seizure (1); triple-negative breast carcinoma (1).
A further 1 disease shares a sentence with ZDHHC9 in 1 paper.